AR (androgen receptor)
Diseases named in the same sentence as AR in open-access papers (continued):
Sharing a sentence is not in itself a finding about the gene and the disease.
bladder cancer (continued). "Based on its common expression in urothelial bladder cancer and its presumed role in cancer progression, therapies targeting AR have been suggested for bladder cancer patients." (PMID 41463239, 2025). "The sex-specific differences in urothelial cancer, particularly male dominance in the incidence of bladder cancer, implied the involvement of AR signaling in urothelial tumorigenesis." (PMID 40486871, 2025). "For bladder cancer, at least 19 studies analyzing between 9 and 472 urothelial carcinomas have described detectable AR expression in 13–77% of cases." (PMID 41463239, 2025). "Silodosin treatment resulted in significant reduction in the viability and migration of AR-positive bladder cancer cells in a dose-dependent manner, while inhibiting ELK1 expression." (PMID 40486871, 2025). "As seen in AR signals, ERβ has been linked to a tumor suppressor FOXO1, as a downstream target, in bladder cancer cells." (PMID 40486871, 2025). "Several studies compared AR-FL protein levels between the bladder cancer and healthy tissues and the results are controversial." (PMID 39083104, 2024). "Our study reached new and valuable findings and will shed light on the studies that aim to clarify the role of the AR pathway in bladder cancer." (PMID 39083104, 2024). "AR-FL mRNA positivity was %4 in bladder cancer group and 92% in control group while AR-V7 mRNA positivity was 17% in bladder cancer group and %83 in control group (p = 0,03 and < 0,001 respectively)." (PMID 39083104, 2024). "Our outcomes obtained by a novel approach at both mRNA and protein levels of AR-FL and AR-V7 will shed light on the studies that will clarify the mechanism of AR pathway in bladder cancer development." (PMID 39083104, 2024). "Among a high portion of male patients with bladder cancer and expressing AR, the combination of AR inhibitor, Enzalutamide, and CDDP synergistically inhibited bladder cancer cell growth more effectively than single agent alone." (PMID 39680264, 2024). "Owing to a growing body of work that strongly suggests AR signaling to be a therapeutic vulnerability in bladder cancer, several recent and upcoming trials will evaluate anti-androgen treatments in prospective clinical cohorts." (PMID 38398136, 2024). "The potentially profound effects of androgens and AR signaling on bladder cancer have prompted many investigators to study mechanistic links to the AR within bladder cancer models." (PMID 38398136, 2024). "The increase of AR-FL protein in bladder cancer supports the contribution of the AR pathway in bladder cancer." (PMID 39083104, 2024). "In contrast, siNEU3 treatment reduced the activation or expression of ERK, PI3K, and androgen receptor, which are involved in the invasiveness of bladder cancer." (PMID 38255300, 2024). "For the BLCA dataset, among the biomarkers identified from the SNV data, it has been revealed that EGF promotes bladder cancer cell proliferation via modulation of AR signals." (PMID 38678587, 2024). "Our study is the first to analyse AR-V7 mRNA and protein levels in bladder cancer along with AR-FL, and even the first one to show the presence of AR-V7 in bladder tissue." (PMID 39083104, 2024). "Our study is the first to examine AR-FL mRNA and AR-FL protein levels simultaneously in bladder cancer." (PMID 39083104, 2024). "We had originally identified LPHN3 as a potential AR target from our DNA microarray analysis in a control AR-positive bladder cancer UMUC3 cell line versus an AR-knockdown UMUC3 subline stably expressing AR-shRNA." (PMID 39000396, 2024). "Some studies found that androgen deprivation by androgen receptor modulation impacted the prognosis and treatment of bladder cancer both in vivo and in vitro." (PMID 38357083, 2024). "Preclinical and clinical data suggest that androgen receptor signaling strongly contributes to bladder cancer development." (PMID 38398136, 2024).
bladder cancer (continued). "Some authors reported higher levels of AR-FL protein in bladder cancer while others reported the opposite." (PMID 39083104, 2024). "Better understanding of these steps will provide evidence for the use of AR-targeted therapies in the treatment of bladder cancer." (PMID 39083104, 2024). "We also believe that the main role player for bladder cancer development is increased AR-FL protein in this pathway." (PMID 39083104, 2024). "We also examined the expression of the androgen receptor, which has been reported to be involved in bladder cancer invasion, and found that it was decreased in siNEU3-treated cells." (PMID 38255300, 2024). "Meanwhile, we have separately demonstrated that androgens activate the EGFR-ERK1/2 pathway in AR-positive bladder cancer cells." (PMID 37762034, 2023). "Based on our studies and pathologists’ clinical experience, the experts stated that the bladder is not generally considered to be an androgen-responsive organ, so we confirmed that AR expression was low in bladder cancer tissues, even in male samples." (PMID 37328487, 2023). "In bladder cancer, AR increases the levels of circFNTA to promote cancer cell invasion and cisplatin chemoresistance." (PMID 37369946, 2023). "A chromatin immunoprecipitation assay further revealed the binding of AR to the promoter region of GABBR2 in bladder cancer cells." (PMID 37762034, 2023). "In AR-positive bladder cancer cells, excess androgen decreases cell sensitivity to cisplatin, whereas AR-negative bladder cancer cells are significantly more sensitive to cisplatin." (PMID 37666817, 2023). "We then found that knockdown of GABBR2 via its shRNA or its inactivation via a GABA B receptor antagonist enhanced the cytotoxic effects of CDDP in AR-positive bladder cancer cells." (PMID 37762034, 2023). "We identified GABBR2 as a key downstream effector of AR in modulating CDDP sensitivity in bladder cancer." (PMID 37762034, 2023). "In AR-positive bladder cancer cells, knockdown of GABBR2 or treatment with a selective GABA B receptor antagonist, CGP46381, considerably enhanced the cytotoxic activity of cisplatin." (PMID 37762034, 2023). "Hormonal influences, exemplified by estrogen and androgen receptor expression on bladder cancer cells, contribute to variations in hormone-targeted therapy responses." (PMID 38283839, 2023). "An in vivo study utilizing the BBN mouse model, a carcinogen-induced model of bladder cancer, revealed a possible mechanism by which AR contributes to sex differences in bladder cancer." (PMID 37666817, 2023). "The observed sex disparity in bladder cancer (BlCa) argues that androgen receptor (AR) signaling has a role in these malignancies." (PMID 36720985, 2023). "Nonetheless, CGP46381 treatment in three AR-positive bladder cancer cell lines, as well as GABBR2 knockdown in UMUC3 cells, did not significantly change their proliferation (via MTT assay) or migration (via wound-healing assay)." (PMID 37762034, 2023). "In the present study, we further investigated the functional role of GABBR2 in CDDP resistance in bladder cancer in relation to AR signaling." (PMID 37762034, 2023). "Accordingly, inhibition of GABBR2 has the potential of being a means of chemosensitization, especially in patients with AR/GABBR2-positive bladder cancer." (PMID 37762034, 2023). "Further, treatment with androgen deprivation therapy, anti-androgens, or small interfering RNA (siRNA) against AR decreased proliferation and tumor growth in animal models of bladder cancer." (PMID 37666817, 2023). "We first demonstrated that AR directly regulated the expression of GABBR2 via binding to its promoter in bladder cancer cells." (PMID 37762034, 2023). "Although both ERβ and AR seem to influence bladder cancer, they are expressed at similar levels in the bladder tumors of patients with male and female gonads." (PMID 37666817, 2023).
bladder cancer (continued). "The androgen receptor (AR), a ligand-activated transcription factor, controls genes that are crucial for male sexual differentiation and development, and its involvement in bladder cancer carcinogenesis has been reported." (PMID 38254939, 2023). "By contrast, the overexpression of AR resulted in an increase in the expression of PD-L1, and the knockdown of AR by shRNA led to a decrease in the expression of PD-L1 in bladder cancer cells." (PMID 37373038, 2023). "We had recently employed DNA microarray analysis in control AR-positive bladder cancer UMUC3 cells versus a subline of UMUC3 stably expressing AR-shRNA." (PMID 37762034, 2023). "In bladder cancers, the expression of AR has been correlated with tumor progression and poor treatment outcomes." (PMID 35053220, 2022). "AR expression appears to be downregulated in bladder cancer immunohistochemistry investigations, and this downregulation tends to increase with increasing tumor stage and grade." (PMID 36042998, 2022). "LncRNA XIST (X-inactive specific transcript) inhibits miR-124 in three types of cancer: bladder cancer, laryngeal squamous cell carcinoma, and tongue squamous cell carcinoma, which activates AR (androgen receptor), EZH2 and JAG1 (jagged 1) proteins." (PMID 36362406, 2022). "In particular, literature has focused on the role of the androgen receptor (AR) in both carcinogenesis and progression of bladder cancer." (PMID 35992775, 2022). "Recently, two papers have been published showing that testosterone has been identified as a novel crucial factor for immunotherapy in prostate and bladder carcinoma by directly diminishing CD8+ T cell function via the androgen receptor." (PMID 35625643, 2022). "The underlying molecular mechanisms of resistance to cisplatin-based systemic chemotherapy in bladder cancer patients remain to be elucidated, while the link between androgen receptor (AR) activity and chemosensitivity in urothelial cancer has been implicated." (PMID 34576193, 2021). "A new axis AR/ADAR2/circFNTA/miR-370-3p/FNTA/KRAS for bladder cancer progression has been discovered." (PMID 33919565, 2021). "Another study has indicated parallel over-expressions of XIST and androgen receptor (AR) in bladder cancer cells." (PMID 34179019, 2021). "Androgens have also been shown to activate ERK, as well as ATF2 which can be phosphorylated in response to phospho-ERK signals, in bladder cancer cells via the AR pathway." (PMID 33652650, 2021). "The present study aimed to investigate how androgen receptor signaling, which is activated by binding of androgenic hormones, modulates sensitivity to cisplatin treatment in bladder cancer, using cell line models and surgical specimens." (PMID 33652650, 2021). "AR is likely to be relatively suppressed in people with small prostates, thereby suppressing the recurrence and progression of bladder cancer." (PMID 34552102, 2021). "Our DNA microarray analysis in control vs. AR knockdown bladder cancer lines identified GULP1 as a potential target of AR signaling." (PMID 34576193, 2021). "Because our DNA microarray analysis in control vs. AR-knockdown bladder cancer lines identified BXDC2 as a potential downstream target of AR, we herein assessed its functional role in cisplatin sensitivity, using bladder cancer lines and surgical specimens." (PMID 33652650, 2021). "We identified GULP1 as a key downstream effector of AR in modulating CDDP sensitivity in bladder cancer." (PMID 34576193, 2021). "Epidermal growth factor (EGF) has also been shown to promote the growth of bladder cancer cells via the AR pathway." (PMID 34064926, 2021). "For example, bladder cancer is characterized by high expression of AR in tumors of low stage and grade and these features positively affect the survival time of patients." (PMID 34440475, 2021).
bladder cancer (continued). "In this article, we summarize the available data that help to explain the role of the AR in the development and progression of bladder cancer, as well as the therapies used for its treatment." (PMID 33919565, 2021). "For instance, experiments in two AR-positive bladder cancer cell lines have shown that phenyl glucosamine can inactivate and degrade AR through the restoration of miR-449a expression." (PMID 34831421, 2021). "Based on these results, we concur that recurrence of bladder cancer is more likely to be due to AR signaling." (PMID 34552102, 2021). "Given the reports, TIL-B cells promote the bladder cancer metastasizing process by modulating the signals of IL-8/androgen receptor (AR)/MMPs." (PMID 34235074, 2021). "XIST silencing has decreased proliferation, invasion, and migratory potential of bladder cancer through modulation of AR signaling." (PMID 34831421, 2021). "The AR plays a role in bladder cancer through many mechanisms that involve the steps of carcinogenesis." (PMID 33919565, 2021). "Several investigations have shown evidence that the AR plays an important role in the initiation and development of different types of cancer including bladder cancer." (PMID 33919565, 2021). "Our recent DNA microarray analysis identified candidate genes, including BXDC2 whose expression was significantly upregulated in an AR-knockdown bladder cancer subline, compared with AR-positive control cells." (PMID 33652650, 2021). "In one of our studies, epidermal growth factor receptor (EGFR)-ERK signaling activation by AR in bladder cancer cells has also been documented." (PMID 33652650, 2021). "It is thus likely that GULP1 represents a key downstream effector of AR signaling in modulating CDDP sensitivity in bladder cancer." (PMID 34576193, 2021). "Specifically, androgens, such as dihydrotestosterone (DHT) and methyltrienolone (R1881), induced cell proliferation, migration, and invasion in bladder cancer lines expressing a functional AR." (PMID 34064926, 2021). "Bladder tissue is not recognized as a hormone-dependent tissue, but studies have shown that ERs and the AR are involved in bladder cancer initiation and progression." (PMID 34771623, 2021). "In addition to chemoresistance, AR signaling in urothelial cancer cells has been implicated in urothelial tumorigenesis and tumor progression, the former of which may clearly explain male dominance in the incidence of bladder cancer." (PMID 33652650, 2021). "While AR activity must be considerably higher in men than in women, no studies have demonstrated significant sex-related differences in the prognosis of bladder cancer patients who undergo systemic chemotherapy." (PMID 34576193, 2021). "The aim of this review is to collect the most recent information on the role of androgens and the AR in the development and progression of bladder cancer, as well as the signaling pathways involved and new therapies." (PMID 33919565, 2021). "Particularly, it has been documented, using preclinical models for bladder cancer induced by known carcinogens in humans such as amine and tobacco smoking, that AR knockdown results in strong prevention in its development." (PMID 34064926, 2021). "In bladder cancer cells, UM-UC-3, the AR influences autophagy by regulating ULK2; in presence of an AR knockdown, the mRNA and protein level of ULK2 are up-regulated, but with DHT treatment, the protein expression of ULK2 decreased." (PMID 33919565, 2021). "Next, we investigated the role of AR in several cancer‐related pathways using a new AR‐positive bladder cancer cell line model, UM‐UC‐3‐AR." (PMID 33797847, 2021). "In other male-dominant cancer, such as hepatocellular carcinoma or bladder cancer, AR and androgen are reported to involve in carcinogenesis and associate with worse outcomes." (PMID 33947843, 2021). "We identified BXDC2 as a key downstream effector of AR in modulating CDDP sensitivity in bladder cancer." (PMID 33652650, 2021).
bladder cancer (continued). "In AR-positive bladder cancer cells, DHT induced the expression of phospho-ATF2 and phospho-ERK as well as nuclear translocation and transcriptional activity of ATF2." (PMID 32759680, 2020). "Biochemical studies revealed that KDM7A knockdown in the bladder cancer cells repressed the activity of androgen receptor (AR) through epigenetic regulation." (PMID 32781788, 2020). "Enzalutamide, a synthetic androgen receptor (AR) signaling inhibitor, synergistically inhibited growth of bladder cancer cells more efficiently when combined with cisplatin." (PMID 33585182, 2020). "When we developed a cisplatin-resistant bladder cancer cell line, we found that AR expression was highly elevated." (PMID 32781788, 2020). "Since AR is known to be essential for cell growth in many cancers, we treated AR siRNA or enzalutamide, to confirm the growth inhibition effect on bladder cancer cell growth." (PMID 32781788, 2020). "Researches regarding the molecular mechanisms of bladder cancer carcinogenesis has outlined the potential role the androgen receptor (AR) plays." (PMID 32917158, 2020). "In the present study, we have further investigated the role of KDM7A in the epigenetic regulation of AR in BCa, with a focus on the regulation of AR activity in the cisplatin-resistant bladder cancer cells." (PMID 32781788, 2020). "In this paper, we focused on the AR function in bladder cancer, because of its high malignant character, which is known to be related to AR malfunction." (PMID 32781788, 2020). "In AR-positive bladder cancer cells, we demonstrated that androgens induced the nuclear expression of β-catenin and its interaction with AR, along with c-myc expression, and thereby activated the Wnt/β-catenin signaling pathway." (PMID 32759680, 2020). "Recent preclinical studies have suggested that the androgen-mediated AR signaling promotes bladder cancer progression, and blocking this signaling with enzalutamide can strongly impair bladder cancer cell growth." (PMID 32781788, 2020). "In order to investigate the possible role of KDM7A demethylase in the functioning of AR in bladder cancer cells, we first compared the AR expression levels in various bladder cancer cell lines, including 253J, RT4, T24, and J82." (PMID 32781788, 2020). "Nonetheless, we were able to detect AR mRNA and protein in the bladder cancer cells that we tested, with the levels found to be comparable among them." (PMID 32781788, 2020). "The effect of AR induction on the cisplatin resistance process of bladder cancer has been previously reported." (PMID 32781788, 2020). "In our study, we evaluated the AR expression in bladder cancer patients and found that AR-positive expressions correlated with decreased risk of recurrence." (PMID 32104638, 2020). "Our data confirmed the molecular function of KDM7A on AR transcription factor activity in bladder cancer cells." (PMID 32781788, 2020). "In bladder cancer cell lines AR expression was marginally upregulated (1.2-fold) only in transitional cancer cell line T24." (PMID 31119584, 2019). "The aim of present study was to elucidate the mechanism of androgen/AR signaling in promotion of bladder cancer in male patients." (PMID 31119584, 2019). "As androgen receptor (AR) reportedly affects bladder cancer, we assessed the correlation between NMIBC recurrence and tumor AR expression in Japanese patients." (PMID 30961575, 2019). "Using molecular classification in bladder cancer cell line models, we recognized that bladder cell lines showed differential expression of androgen receptor in male origins cell lines and responded differently to androgen stimulation." (PMID 31119584, 2019).